ARB2A (ARB2 cotranscriptional regulator A)
Description:
Plays a role in the regulation of alternative splicing, by interacting with AGO2 and CHD7. Seems to be required for stabilizing protein-protein interactions at the chromatin-spliceosome interface. May have hydrolase activity.
Synonyms: C5orf21; FAM172A; DKFZP564D172; Toupee
Tractability: Antibody: UniProt predicts a signal peptide or a membrane-spanning region. PROTAC: ubiquitination databases record sites on it.
Gene: Protein-coding gene on chromosome 5 (93,615,442 to 94,111,699, reverse strand). Ensembl gene ENSG00000113391.
Subcellular location: Nucleus; Cytoplasm; Endoplasmic reticulum
Subcellular location (Human Protein Atlas): Nucleoplasm; Cytosol
Gene Ontology:
Molecular function: protein binding; siRNA binding
Biological process: neural crest cell development; regulation of alternative mRNA splicing, via spliceosome; regulatory ncRNA-mediated heterochromatin formation
Cellular component: cytosol; endoplasmic reticulum; nucleoplasm; cytoplasm; nucleus
Genetic constraint (gnomAD): Loss-of-function variants: 20 observed, 29.47 expected, observed/expected ratio (o/e) 0.68, 90% interval 0.48 to 0.99. The upper end of that interval is the gene's LOEUF score, 0.99, which puts it in group 4 of 6, group 1 being the genes least tolerant of losing a copy. Missense variants: 387 observed, 392.56 expected, observed/expected ratio (o/e) 0.99, 90% interval 0.91 to 1.07. Synonymous variants: 131 observed, 135.98 expected, observed/expected ratio (o/e) 0.96, 90% interval 0.83 to 1.11.
Homologues: Orthologues: pig ARB2A (98% identical), dog ARB2A (97% identical), mouse Arb2a (93% identical), macaque ARB2A (93% identical), chimpanzee ARB2A (90% identical), rabbit ARB2A (89% identical), rat Arb2a (86% identical), tropical clawed frog arb2a (81% identical), zebrafish arb2a (74% identical), guinea pig ARB2A (69% identical), Drosophila melanogaster CG10038 (29% identical), Caenorhabditis elegans Y75B8A.31 (25% identical).
Diseases named in the same sentence as ARB2A in open-access papers:
ARB2A is named in the same sentence as 21 diseases in open-access papers, as found by Europe PMC text mining. Sharing a sentence is not in itself a finding about the gene and the disease.
ARB2A shares sentences with these, for which no sentence is quoted: cancer (4 papers); pancreatic cancer (4); tumor (4); CHARGE syndrome (3); colorectal cancer (3); papillary thyroid carcinoma (3); colon cancer (2); follicular thyroid cancer (2); teratozoospermia (2); Anxiety (1); atherosclerosis (1); Azoospermia (1); epithelial ovarian cancer (1); fibrosis (1); HCMV infection (1); infection (1); lymph node metastasis (1); Obesity (1); serous carcinoma (1); thyroid tumor (1); viral infection (1).